RAC3 (Rac family small GTPase 3)
Diseases named in the same sentence as RAC3 in open-access papers (continued):
Sharing a sentence is not in itself a finding about the gene and the disease.
tumor (continued). "Numerous studies have shown that RAC3 is involved in tumor invasion and metastasis 25, 26, which drove us to further investigate whether RAC3 played a role in NSCLC cells migration." (PMID 37056933, 2023). "Thus, the high‐level expression of RAC3 in EC orchestrated an immunosuppressive microenvironment and promoted tumour progression." (PMID 37386813, 2023). "There is increasing evidence that RAC3 is involved in tumor progression." (PMID 37056933, 2023). "Notably, TCGA database analysis indicated that RAC3 was upregulated in both LUAD and LUSC tissues compared with non-tumor tissues, suggesting the potential of RAC3 as a therapeutic target." (PMID 37056933, 2023). "In conclusion, AP2S1, P3H4, and RAC3 were identified as candidate tumor-specific antigens in BLCA, and BCS2 and BCS1A patients may benefit from mRNA vaccine therapy." (PMID 35814377, 2022). "AP2S1, P3H4, and RAC3 were identified as candidate tumor-specific antigens for BLCA." (PMID 35814377, 2022). "Sequencing data analysis of GTEx+TCGA showed the RAC3 mRNA was higher in most tumors than that in non-tumor tissues, whether in all samples or paired samples." (PMID 35847878, 2022). "Below are summarized the studies that have revealed the implication of Rac3 in tumor progression, and that have addressed some of the mechanisms by which this GTPase may act specifically in different types of tumor cells." (PMID 31514269, 2019). "In fact, RAC3 is an oncogene that contributes to tumor development acting as a nuclear receptor coactivator of several transcription factors that control the expression of genes related to cell cycle progression and proliferation, inhibition of apoptosis, autophagy and senescence." (PMID 29464039, 2018). "Although these RAC3 overexpressing cells induced a rapid tumor growth when were inoculated in vivo in nude mice, their ability to be differentiated toward other several tissues was not demonstrated in the present work, afterwards, their classification as “stem cells” is not completely suitable." (PMID 29464039, 2018). "Therefore, with RAC3 being a molecule whose overexpression contributes to tumor development, inhibiting apoptosis and autophagy, we decided to investigate its probable role in cellular senescence." (PMID 26469953, 2015). "Differences arise in the immediate outputs—glutaminolysis via SLC7A5 in NSCLC, fatty-acid activation via ACSL3 in CRC, and pro-migratory signaling via RAC3—and in whether CAFs act primarily by secreting a writer versus inducing tumor writers through growth-factor signaling." (PMID 41280938, 2025). "However, the precise mechanisms by which RAC3 contributes to the malignancy of tumor cells remain unclear." (PMID 39351351, 2024). "Moreover, our results suggested that RAC3 was related to poor prognosis, which might be due to immunosuppressive effects and proliferation‐promoting effects on tumour cells." (PMID 37386813, 2023). "However, depletion of Rac3 or RhoG increased tumor cell diapedesis." (PMID 21776386, 2011). "Univariate analysis further demonstrated that tumor size (p = 0.016), tumor grade (p = 0.027), tumor capsule integrity (p = 0.045), TNM stage (p = 0.006), and RAC3 expression (p = 0.005) were notably related to OS." (PMID 40123831, 2025). "Similar to what was observed on the transcription level, GTPase-related pathways—notably, those involving RAC1, RAC3, and RAS proteins—were significantly enriched in the tumor cells." (PMID 40724880, 2025). "Differential expression analysis of 10 genes in tumor and normal tissues showed that RAC3 and PTPRR were highly expressed in tumor tissues, while the rest of the genes were lowly expressed in tumors (p < 0.05)." (PMID 38714855, 2024). "Notably, the group with increased RAC3 expression had significantly lower scores in all measured categories (p=0.035, p<0.0001, and p=0.00031), and a clear positive correlation between RAC3 levels and tumor purity was observed, indicating a potential role of RAC3 in modulating the TME." (PMID 39351351, 2024).
tumor (continued). "Compared to normal tissues, tumor tissues displayed a significant increase in staining intensity for PTPRR and RAC3." (PMID 38714855, 2024). "RAC3 was identified as a potential therapeutic target and biomarker of BLCA, as its expression significantly influenced tumor progression, the immune response, and chemosensitivity." (PMID 39351351, 2024). "The results indicated that RAC3 was mainly co‐localized with EPCAM, a considerable marker highly expressed in epithelial tumour cells." (PMID 37386813, 2023). "We compared the expression levels of IGF2BP3, P4HB, RAC3 and CLK2 in TCGA BCa tissues and normal tissues, and the results showed that all four genes were significantly upregulated in tumor tissues." (PMID 38299148, 2023). "Several critical proteins in tumor development and progression, such as PTEN, MAPK8, CUL1, and RAC3, were enriched." (PMID 35990607, 2022). "In total, three potential tumor-specific antigens (AP2S1, P3H4, RAC3) were identified for mRNA vaccine research." (PMID 35814377, 2022). "When we analyzed the expression levels of RAC3 in patients of the IDIM hospital population and its correlation with the tumor stage, the results obtained show a tendency similar to that reported by other authors." (PMID 29209153, 2017). "In CRC studies, a copy number gain of RAC3 was detected in 27.5% and it is overexpressed in 35% CRC samples correlating with tumor progression." (PMID 29209153, 2017). "The RAC3 expression levels did not significantly correlate with age, BMI, clinical stage and tumour invasion." (PMID 37386813, 2023). "In the TCGA-UCEC dataset, APOBEC3G, CUL4B, SCML2, TSPYL5, and ZBTB16 were significantly downregulated in tumor samples, whereas FOXP3, HJURP, HMGB3, and RAC3 were significantly upregulated in tumor samples, which was generally consistent with the result observed in GSE17025." (PMID 36936912, 2023). "Recurrence free survival was shorter and metastatic events higher among women with ERα—positive tumors that have increased expression of mRNA for Rac3, while the expression of the mRNA for Rac3 does not correlate with metastasis in ERα—negative tumor samples." (PMID 31514269, 2019). "Here, results highlighting the importance of Rac3 in distinct aspects of neuronal development and tumor cell biology are presented, in support of the non-redundant role of different members of the two Rac GTPases in physiological and pathological processes." (PMID 31514269, 2019). "Further, we demonstrate that Rac1 GTPase has a significant effect on PCa cell diapedesis, while Rac3 has a negative effect on tumor cell diapedesis." (PMID 21776386, 2011). "Notably, CSNK1E and RAC3 demonstrated a significant correlation with EMT, indicating their potential involvement in mediating the metastatic process of MM cells, as EMT facilitates tumor cell invasion through the basement membrane into the bloodstream." (PMID 39872053, 2024). "Furthermore, RAC3 accelerated tumour cell proliferation and inhibited its apoptosis, without impacting cell cycle stages." (PMID 37386813, 2023). "Furthermore, RAC3 accelerated tumor cell proliferation and inhibited its apoptosis, without impacting cell cycle stages." (PMID 37927462, 2023). "Subsequent studies showed that RAC3 was involved in the regulation of the cell cycle, cell proliferation, apoptosis, the inhibition of autophagy, cell migration, and epithelial–mesenchymal transition (EMT), all of which are closely related to tumor development." (PMID 33782686, 2021). "This suggests a negative effect of Rac3 and possibly RhoG on tumor cell diapedesis." (PMID 21776386, 2011). "Thus, this system might be likely to reflect the activation of endogenous Rac1 mainly in the patients’ tumor tissues, although activation of other Rac members, such as Rac2 and Rac3 and/or Cdc42 cannot be ruled out." (PMID 35110666, 2022).
neurodevelopmental disorder (5 papers, 2019 to 2025). A behavioral and cognitive disorder with onset during the developmental period that involves impaired or aberrant development of intellectual, motor, or social functions. "De novo deleterious variants in RAC3 cause neurodevelopmental disorder with structural brain anomalies and dysmorphic facies (NEDBAF)." (PMID 40015633, 2025). "To date, 12 de novo missense variants in RAC3 have been associated with a clinically heterogeneous disorder known as NEurodevelopmental Disorder with Brain Anomalies and dysmorphic Facies (NEDBAF, MIM #618577)." (PMID 39682779, 2024). "Variants in RAC3, encoding a small GTPase RAC3 which is critical for the regulation of actin cytoskeleton and intracellular signal transduction, are associated with a rare neurodevelopmental disorder with structural brain anomalies and facial dysmorphism." (PMID 35851598, 2022). "Pathogenic variants in RAC3, all of which reported thus far affect conserved residues within its functional domains, have been linked to neurodevelopmental disorders characterized by diverse phenotypic features, including structural brain anomalies and facial dysmorphism (NEDBAF)." (PMID 39682779, 2024). "RAC1, RAC3, and CDC42 (another Rho family member) are critical regulators of brain development, and disruptions in their signaling pathways have been implicated in various neurodevelopmental disorders (NDDs)." (PMID 39682779, 2024). "Until now, square frontal horns have not been reported to be associated with RAC3-related neurodevelopmental disorders." (PMID 38214746, 2024).
infection (2 papers, 2024 to 2025). The state of being infected such as from the introduction of a foreign agent such as serum, vaccine, antigenic substance or organism. "Cells expressing SV40, C-MYC, HNRNP K, HNRNP A1 and Rac3 chimeras supported P90A infection to a similar degree as observed for WT HIV-1." (PMID 38979149, 2024). "We found that the C-MYC and Rac3 NLS not only fully rescued infection, but resulted in a small but significant increase in infectivity compared to the infection observed in CPSF6-KO and CPSF6-FL cells." (PMID 38979149, 2024).
RAC3 also shares sentences with these, for which no sentence is quoted: chronic cystitis (2 papers); heterotopia (2); breast tumors (1); colorectal tumors (1); corpus callosum agenesis (1); cutaneous melanoma (1); developmental delay (1); Ewing sarcoma (1); hearing loss (1); Mental Retardation autosomal dominant 48 (1); neurological disorders (1); pancreatic cancer (1); pneumonitis (1); respiratory diseases (1); schizophrenia (1); serous ovarian cancer (1); syntelencephaly (1); Talipes equinovarus (1); thyroid carcinoma (1).